FOXP3 (forkhead box P3)
Diseases named in the same sentence as FOXP3 in open-access papers (continued):
Sharing a sentence is not in itself a finding about the gene and the disease.
neurodegenerative disease (3 papers, 2013 to 2022). A disorder of the central nervous system characterized by gradual and progressive loss of neural tissue and neurologic function. "Accumulation of pan‐pTreg cells in aged individuals was demonstrated to be harmful during neurodegenerative disease AD, since transient inhibition of FoxP3 expression in the accumulated pTreg cells attenuated AD pathology." (PMID 35615905, 2022). "Our study revealed that genes negatively correlated with FOXP3 were enriched in pathways such as neurodegenerative disease-related pathways and oxidative phosphorylation pathway." (PMID 34006632, 2021). "Dysfunction of FoxP3+CD25+CD4+ Tregs was observed in the early stages of several neurodegenerative diseases." (PMID 23983771, 2013). "The importance of FoxP3+CD25+CD4+ Tregs in regulating and maintaining homeostasis between both the immune system and the brain is demonstrated by their roles in CNS diseases, especially neurodegenerative diseases, such as MS, Parkinson's disease (PD) and Alzheimer's disease (AD)." (PMID 23983771, 2013).
central nervous system diseases (2 papers, 2013 to 2018). "The positive influence of CD4+ FoxP3+ regulatory T cells on remyelination was proven in demyelinating central nervous system disorders such as multiple sclerosis." (PMID 29618748, 2018).
connective tissue diseases (2 papers, 2021 to 2023). "Additionally, the association of the TC genotype of Foxp3 rs2280883 was found with the risk of connective-tissue-disease-associated ILD." (PMID 37998578, 2023).
heart disease (2 papers, 2014 to 2019). "Therefore, we tested the subtypes of Th1 (CD4+IFNγ+), Th2 (CD4+IL4+), and Treg (CD4+CD25+Foxp3+) cells, which influence inflammation associated with heart disease." (PMID 31547872, 2019).
intestinal disease (2 papers, 2018 to 2024). "CIR rich cells were able to prevent intestinal disease to a similar extent as Foxp3+ Treg cells." (PMID 30575716, 2018).
gastrointestinal disease (1 paper, 2012). A disease that occurs in the gastrointestinal system, excluding the hepatobiliary system. "Foxp3 expressing lymphocytes in dogs suffering from gastrointestinal diseases." (PMID 22440243, 2012). "Foxp3 expressing lymphocytes in dogs without gastrointestinal diseases." (PMID 22440243, 2012).
hematological cancer (1 paper, 2023). "Several studies suggested that pTregs favor both solid and hematological cancer growth independently of CD25 and FoxP3 expression." (PMID 36901957, 2023).
inflammatory myopathies (1 paper, 2015). "FOXP3‐positive regulatory T cells have recently been reported to reside in muscles from inflammatory myopathies including sIBM and, interestingly, their number is proportional to the number of cytotoxic T cells." (PMID 24750247, 2015).
psychiatric disorder (1 paper, 2022). A disorder characterized by behavioral and/or psychological abnormalities, often accompanied by physical symptoms. "This study is one of few studies that focused on the role of FOXP3 in psychiatric disorders." (PMID 35641708, 2022).
FOXP3 also shares sentences with these, for which no sentence is quoted: multiple myeloma (9 papers); eczema (8); kidney (8); autoimmune enteropathy (6); Wiskott-Aldrich syndrome (6); alopecia (5); chronic hepatitis (5); endocrinopathy (5); genetic disorder (5); pancreatic adenocarcinoma (5); alopecia areata (4); chronic lymphocytic leukemia (4); enterocolitis (4); intestinal tuberculosis (4); invasive ductal carcinoma (4); viral disease (4); angina (3); autoimmune polyendocrinopathy (3); Cerebral ischemia (3); chronic periodontitis (3); egg allergy (3); fetal hydrops (3); Flavivirus Infections (3); hyperthyroidism (3); hypothyroidism (3); incontinentia pigmenti (3); lichen planus (3); Myelopathy (3); psoriasis vulgaris (3); squamous intraepithelial lesions (3).
A further 248 diseases each share a sentence with FOXP3 in 3 papers or fewer.